LRRC61 (leucine rich repeat containing 61)
Synonyms: MGC3036; FLJ31392; HSPC295
Tractability: PROTAC: ubiquitination databases record sites on it.
Gene: Protein-coding gene on chromosome 7 (150,323,263 to 150,338,156, forward strand). Ensembl gene ENSG00000127399.
Subcellular location (Human Protein Atlas): Nucleoplasm
Gene Ontology:
Molecular function: protein binding
Genetic constraint (gnomAD): Loss-of-function variants: 13 observed, 16.66 expected, observed/expected ratio (o/e) 0.78, 90% interval 0.51 to 1.24. The upper end of that interval is the gene's LOEUF score, 1.24, which puts it in group 5 of 6, group 1 being the genes least tolerant of losing a copy. Missense variants: 344 observed, 318.85 expected, observed/expected ratio (o/e) 1.08, 90% interval 0.99 to 1.18. Synonymous variants: 173 observed, 151.03 expected, observed/expected ratio (o/e) 1.15, 90% interval 1.01 to 1.3.
Homologues: Orthologues: chimpanzee LRRC61 (99% identical), guinea pig LRRC61 (88% identical), mouse Lrrc61 (88% identical), pig LRRC61 (87% identical), rat Lrrc61 (86% identical), macaque LRRC61 (79% identical), tropical clawed frog lrrc61 (53% identical), zebrafish lrrc61 (48% identical), Drosophila melanogaster TbCMF46 (15% identical), Drosophila melanogaster Ppr-Y (14% identical). Paralogues in human: LRRC9 (24% identical), CEP97 (22% identical), LRRC49 (21% identical), LRGUK (20% identical), DNAAF1 (19% identical), LRRC43 (19% identical), LRRCC1 (18% identical), DRC3 (17% identical), LRRC46 (17% identical), DNAAF11 (16% identical), PPP1R42 (15% identical), LRRC23 (14% identical), and 1 more.
Diseases named in the same sentence as LRRC61 in open-access papers:
LRRC61 is named in the same sentence as 1 disease in open-access papers, as found by Europe PMC text mining. Sharing a sentence is not in itself a finding about the gene and the disease. The quoted sentences say what the papers report.
cancer (1 paper, 2023). A tumor composed of atypical neoplastic, often pleomorphic cells that invade other tissues. "For example, MAD2L2 and LRRC61 are risk factors in most cancers, while PFKFB3, ESAM, SYNM, and LRFN5 act as protective factors in most cancers." (PMID 38124743, 2023).